IL6 (interleukin 6)
Diseases named in the same sentence as IL6 in open-access papers (continued):
Sharing a sentence is not in itself a finding about the gene and the disease.
appendicitis (45 papers, 2006 to 2026). Acute inflammation of the vermiform appendix. "Early evidence indicates that IL-6 can also be detected in saliva, though its diagnostic performance in appendicitis is less well studied than in serum." (PMID 41153524, 2025). "We discovered that preoperative serum levels of IFN-γ, IL-5, IL-6, IL-8, and IL-10 hold diagnostic value in staging pediatric acute appendicitis." (PMID 40150581, 2025). "The association between higher concentrations of IL-6 and complicated appendicitis is in line with the results from previous studies." (PMID 38409170, 2024). "A prospective observational study was performed to verify the diagnostic role of IL-6 in distinguishing between uncomplicated and complicated pediatric appendicitis." (PMID 38892260, 2024). "Nevertheless, this study adds evidence supporting the previously indicated association between IL-6 and complicated appendicitis." (PMID 38409170, 2024). "High serum concentrations of IL-6 were associated with an increased risk of complicated appendicitis in children, whereas serum concentrations of IL-1α, IL-1β, IL-2, IL-10, IL-17A and TNF-β were not." (PMID 38409170, 2024). "After adjustment for age, symptom duration, and presence of appendicolith in a multivariable logistic regression, a higher concentration of IL-6 remained associated with an increased risk of complicated appendicitis (aOR 1.001 [95% CI 1.000–1.002], p = 0.02)." (PMID 38409170, 2024). "The diagnostic value of IL-6 and its capacity to indicate the extent of appendicitis has been evaluated." (PMID 38892260, 2024). "After adjusting for known risk factors such as age, symptom duration and the presence of an appendicolith in the multivariable regression analysis, higher concentrations of IL-6 remained associated with an increased risk of complicated appendicitis." (PMID 38409170, 2024). "The association between higher concentration of IL-6 and complicated appendicitis remained in the multivariable analysis after adjustment for age, symptom duration and presence of an appendicolith (OR 1.001 [95% CI 1.000–1.002], p = 0.02)." (PMID 38409170, 2024). "Serum interleukin-6 (IL-6) has a moderate diagnostic performance in pediatric acute appendicitis (PAA)." (PMID 36114365, 2022). "IL-6 can be considered as a biomarker for appendicitis as well, since high serum levels can often be associated with the condition." (PMID 33060696, 2020). "Conversely, novel markers that are less commonly used clinically in the diagnosis of appendicitis such as interleukin-6 have been shown to have a higher diagnostic benefit, but are associated with significant costs." (PMID 27495334, 2017). "Several studies have focused on the diagnostic value of the IL-6 concentration in suspected appendicitis." (PMID 17132173, 2006). "For every 10-unit increase in IL-6, the adjusted risk of complicated appendicitis increased by 1%." (PMID 38409170, 2024). "Although Spanish scientists indicate that the diagnostic performance of IL-6 alone for the diagnosis of acute appendicitis is limited but they also present the evidence regarding its capacity to discern between complicated and uncomplicated appendicitis in children." (PMID 37509519, 2023). "The significantly increased initial levels of IL-6 in patients with inflammation observed in our own research may prove a clinically useful diagnostic marker of appendicitis." (PMID 37509519, 2023). "IL-6 may be utilized as a diagnostic biomarker for complicated appendicitis." (PMID 41711118, 2026). "IL-6 (-572G/C rs1800796) and IL-6R (1:G.154448302 T > C rs7529229) gene polymorphisms may have an impact on cytokine production, immune response and these gene polymorphisms may be used as inflammatory markers in the diagnosis of appendicitis." (PMID 26714766, 2015). "IL-6 had the best performance (area under curve 0.785) in predicting complicated acute appendicitis." (PMID 41711118, 2026).
appendicitis (continued). "The IL-6 levels were significantly higher in patients with acute appendicitis (MD -19.99; 95% CI: -31.19 to -8.79; p = 0.0008; I2 = 73.8%)." (PMID 42079617, 2026). "Compared to uncomplicated appendicitis, complicated appendicitis showed statistically significantly elevated levels in interleukin 6 (IL-6) (p < 0.001), hepatocyte growth factor (HGF) (p = 0.003), and monocyte chemoattractant protein 1 (MCP-1) (p < 0.001)." (PMID 41711118, 2026). "IL-6 was higher in the appendicitis group (median 19.41 vs. 4.10 pg/mL) and showed moderate discrimination (AUC 0.696)." (PMID 42122040, 2026). "A great number of studies have already confirmed the precise involvement of IL-6 and IL-8 in appendicitis staging." (PMID 40150581, 2025). "Other studies have demonstrated that serum IL-6 can differentiate between complicated and uncomplicated appendicitis." (PMID 40150581, 2025). "Recent research demonstrated that serum IL-6 is effective in distinguishing between complicated and uncomplicated cases of pediatric acute appendicitis." (PMID 39735250, 2024). "The aim of the present study was to evaluate how the Th1 and Th17-associated cytokines IL-1α, IL-1β, IL-2, IL-6, IL-10, IL-17A and tumor necrosis factor beta (TNF-β) are associated with the risk of complicated appendicitis in children." (PMID 38409170, 2024). "This was echoed by a retrospective study of children with acute appendicitis, where IL-6 and other biomarkers such as CRP, immunoglobulin E (IgE), and interleukin-13 (IL-13) were found to be independent risk factors for complicated appendicitis (p < 0.05)." (PMID 38892260, 2024). "Children with complicated appendicitis had significantly higher concentrations of serum IL-6 and IL-10, and lower of TNF-β." (PMID 38409170, 2024). "Previous studies have shown that LOS in pediatric appendicitis is influenced by various factors, such as operative time, preoperative inflammatory markers, duration of symptoms, patient age, and interleukin-6 (IL-6)." (PMID 39735250, 2024). "The AUC for IL-6 was found to be 0.75, indicating only a moderate discriminatory ability in predicting complicated pediatric appendicitis." (PMID 38409170, 2024). "There are, however, multiple papers on the role of PTX-3, IL-6, D-dimer, and CRP in other settings of urgent acute abdomen, such as acute appendicitis, one of the main diagnostic entities to consider in the differential diagnosis of ovarian torsion." (PMID 39519217, 2024). "Systematic reviews and studies revealed a possible elevation of IL-6 levels in children with complicated appendicitis." (PMID 38892260, 2024). "When evaluating microslides based on the clinical and morphological forms of acute appendicitis, the highest distribution of IL-1 and IL-6 was observed in the gangrenous form, followed by the phlegmonous form, compared to the catarrhal form." (PMID 38397914, 2024). "A study highlighted the usefulness of interleukin-6 as a biomarker related to patient prognosis, such as hospital stay duration in pediatric appendicitis." (PMID 37894416, 2023). "Research has demonstrated that probiotics can decrease the levels of pro-inflammatory cytokines and chemokines, such as tumor necrosis factor-alpha (TNF-alpha) and interleukin-6 (IL-6), which are typically elevated in acute appendicitis." (PMID 37514986, 2023). "detected in particular increased plasma levels of IL-6 in complicated (complex) compared to uncomplicated (simple) appendicitis." (PMID 38239362, 2023). "A similar cytokine pattern has earlier been described in cases of complicated appendicitis (IL-6, IL-17alfa and IL-10), as well as a more prominent Th1 inflammatory pattern." (PMID 36013568, 2022). "The aim of this study was to investigate the immunohistochemical expression of TNF-α, IL-6, IL-2R and serotonin in appendices resected from adult patients with symptoms of acute appendicitis, including those with histologically normal appendices." (PMID 34392384, 2021).
appendicitis (continued). "As IL-6 is a potent procoagulant leading to gangrene and is associated with the severity of the inflammatory process, the findings of increased IL-6 expression in complicated acute appendicitis support this." (PMID 34392384, 2021). "Leucine-rich α-2-glycoprotein (LRG), 5-HIAA, IL-6, substance P, calprotectin and bilirubin were used for diagnosis of acute appendicitis." (PMID 33898036, 2021). "This article breaks down the previous research on pentraxin-3 and interleukin-6 biomarkers in relation to appendicitis and proposes a new hypothetical way of confirming the diagnosis." (PMID 32983691, 2020). "Patients with complicated appendicitis were reported to have higher plasma IL-6 level than those with simple appendicitis." (PMID 32180028, 2020). "Serum IL-6 and IL-10 were significantly elevated during acute appendicitis, whereas IL-8 was significantly lower during appendicitis." (PMID 33060696, 2020). "The pooled sensitivity of IL-6 for the diagnosis of acute appendicitis was 0.73 (95 % CI 0.67–0.78; I2 = 91.1 %), and its pooled specificity was 0.72 (95 % CI 0.63–0.79; I2 = 62.3 %)." (PMID 27495334, 2017). "It has been shown, that WBC count, serum CRP, and IL-6 are helpful tools to support the clinical diagnosis of phlegmonous and perforated appendicitis in childhood." (PMID 17132173, 2006). "Although IL-6 is considered an inflammatory marker in appendicitis, it does not appear to provide a significant diagnostic advantage over traditional markers like WBC and CRP." (PMID 41153524, 2025). "Future research that integrates IL-6 assessment may further optimize predictive models and provide deeper insights into the role of systemic inflammation in recovery following pediatric appendicitis surgery, including its impact on hospitalization duration." (PMID 39735250, 2024). "However, the AUC for IL-6 was found to be 0.75, indicating only a moderate discriminatory ability in predicting complicated pediatric appendicitis, which is in line with previous studies that have found the AUC for IL-6 to be 0.70–0.7728–30." (PMID 38409170, 2024). "This prospective cohort study aimed to evaluate the association between serum concentrations of the Th1-associated cytokines interleukin (IL)-1α, IL-1β, IL-2, IL-6, IL-10, IL-17A and tumor necrosis factor beta (TNF-β) and the risk of complicated appendicitis in children." (PMID 38409170, 2024). "The results disclosed significantly elevated IL-6 levels in children with complicated appendicitis." (PMID 38892260, 2024). "Our research indicates that parallel assaying of the level of CRP, NGAL and IL-6 increases the probability of diagnosing of appendicitis in paediatric patients presenting at an emergency department with clinical symptoms which suggest the presence of this disease." (PMID 37509519, 2023). "A recent systematic review concluded that the discriminatory capacity of IL-6 to distinguish between PAA and NSAP was only moderate, but the authors also reported that serum level of IL-6 seemed to be correlated with the time of clinical evolution of the appendicitis." (PMID 36114365, 2022). "Therefore, further studies on a multicenter level are needed to explore the role of PTX3 and IL-6 in acute appendicitis alongside the Alvarado Score." (PMID 32983691, 2020). "However, biomarkers such as pentraxin-3 and interleukin-6 have been recently researched to assess the possibility of confirming the diagnosis of acute appendicitis in both adults and the pediatric age group." (PMID 32983691, 2020). "Ozguner and colleagues determined that IL-6 levels may be useful in the prediction of the patients with appendicitis." (PMID 26714766, 2015). "Measurement of IL-6 or CRP but not WBC had additional diagnostic value on the diagnosis of advanced or perforated appendicitis (groups 3 and 4)." (PMID 17132173, 2006).
appendicitis (continued). "While its use solely for diagnosis has been discussed, IL-6 could still serve as an effective predictive biomarker for distinguishing between patients with acute uncomplicated appendicitis and those with complicated appendicitis." (PMID 41153524, 2025). "Moreover, studies have indicated that appendicitis patients with a post-operative IL-6 increase exceeding 10% often experience prolonged hospitalization, potentially due to the association between elevated IL-6 levels and a heightened systemic inflammatory response." (PMID 39735250, 2024). "In sum, the findings presented here together with data from previous studies suggest that aberrant Th17 responses are increased in complex appendicitis and plasma levels of IL-17A and IL-6 may offer potential biomarkers that should be investigated in future studies." (PMID 38239362, 2023). "However, the previous studies show how PTX3 with the aid of IL-6 might change that in the near future by not only diagnosing acute appendicitis but also predicting the likelihood of perforation in those individuals." (PMID 32983691, 2020). "Also, only two of them assessed the association of IL-6 and PTX3 with appendicitis." (PMID 32983691, 2020). "In our cohort, children with complicated appendicitis had significantly higher median concentrations of serum IL-6 and IL-10, and lower median concentrations of serum TNF-β compared to children with uncomplicated appendicitis." (PMID 38409170, 2024). "When comparing the expression of IL-6 between Group II and Group III, a 4.1-fold increase was observed depending on the clinical and morphological forms of acute appendicitis, with significantly higher levels in the gangrenous and perforated forms." (PMID 38397914, 2024). "Significant differences in serum concentrations of IL-6, IL-10, and TNF-β were observed when analyzing cytokine levels between the no appendicitis group, and the uncomplicated and complicated appendicitis groups." (PMID 38409170, 2024). "Meanwhile, the overall accuracy of confirming the diagnosis of acute appendicitis using PTX3 and IL-6 was 97.2% and 90.4%, respectively." (PMID 32983691, 2020). "Serum IL-10 and IL-6 were significantly elevated at presentation, and IL-6, IL-8 and TNF-α levels were higher in complicated appendicitis." (PMID 33060696, 2020). "Significantly higher IL-6 responses towards FSL-1 (p = 0.026) and lower responses towards S. dysgalactiae (p = 0.026) were shown in patients with a history of gangrenous appendicitis." (PMID 33060696, 2020). "At presentation, serum IL-6, IL-8 and TNF-α levels were significantly higher in complicated versus uncomplicated appendicitis patients." (PMID 33060696, 2020). "IL-6, IL-8, and PCT demonstrated the most significant difference (p < 0.001) between simple and complex appendicitis." (PMID 30918467, 2019). "To determine the effect of the ERAS perioperative regimen on postoperative inflammatory status in patients with appendicitis, we measured WBC, CRP, PCT, and IL-6 levels in patients with appendicitis before surgery, 6 h after surgery, and on the third day after surgery." (PMID 37928355, 2023). "Subacute appendicitis cannot be detected by CRP, IL-6 or leukocytes." (PMID 34064691, 2021). "Correlations between IL-10, IL-6, IL-1Ra and MCP-1 indicate that a combination of these factors could be of importance in appendicitis." (PMID 33060696, 2020). "The results suggested the importance of IL-6 and IL-8 in the differentiation of perforative and non-perforative acute appendicitis." (PMID 31615548, 2019). "Similar to our finding some studies have also demonstrated that IL-6 is more elevated in advanced appendicitis compared to non-perforated simple appendicitis." (PMID 29511263, 2018). "Furthermore, IL-6 levels were also found higher in the perforated group, with a median value of 532.2 pg/mL, and in the non-perforated acute appendicitis group, with a median value of 250.8 pg/mL." (PMID 32983691, 2020).
appendicitis (continued). "Our primary objective was to compare levels of individual inflammatory protein mediators previously associated with intra-abdominal inflammation (CRP, PCT, interleukin-6 (IL-6), IL-8, IL-10, and monocyte chemoattractant protein-1 (MCP-1), SAA) in a cohort of children with suspected appendicitis." (PMID 30918467, 2019). "Identification of children with severe appendicitis was supported by IL-6 or CRP but not WBC." (PMID 17132173, 2006). "In our studies, we have demonstrated significantly higher preoperative levels of IL-6 in children with confirmed appendicitis compared to patients without inflammation, which is in accordance with the reports of other authors and may be predictive for diagnosis." (PMID 37509519, 2023). "Furthermore, a criterion for discrimination between phlegmonous and perforated appendicitis could be found not for leukocytes, but for IL-6 and mostly impressive for CRP." (PMID 17132173, 2006). "Serum IL-6 and TNF-α levels in the PA group were higher than those in the non-perforated appendicitis group." (PMID 38892260, 2024). "In comparison to Interleukin-6 (IL-6) and CRP, no other biomarkers have been proven effective in diagnosing appendicitis." (PMID 34064691, 2021). "Plasma levels of IL-6, CRP, MCP-1, PCT, and SAA were significantly different (p < 0.001) in children with appendicitis compared to those with nonappendicitis abdominal pain." (PMID 30918467, 2019).